EZH2 (enhancer of zeste 2 polycomb repressive complex 2 subunit)
Diseases named in the same sentence as EZH2 in open-access papers (continued):
Sharing a sentence is not in itself a finding about the gene and the disease.
lymphoma (continued). "Mice bearing tumors were treated with 200 mg/kg EZH2 inhibitor EPZ-6438 per day, a dose that exhibited dramatic tumor growth inhibition in the preclinical lymphoma xenograft models, and then xenografts were collected." (PMID 36038549, 2022). "Thus, it could be argued that this could be an option for refractory lymphoma patients (or other B cell malignancies) without EZH2 mutation, given its reasonable efficacy and safety profile." (PMID 36684449, 2022). "In turn, PRC2-regulated genes were repressed in isogenic PRAME-KO lymphoma cell lines, and PRAME was found to directly interact with EZH2 as a negative regulator." (PMID 35380993, 2022). "Further, wild-type and mutant EZH2 cooperatively regulate and maintain the hypertrimethylation of H3K27, which inhibits the proliferation of lymphoma cells by abnormally silencing PCR2-target genes." (PMID 35419278, 2022). "In 2020, the EZH2 inhibitor tazemetostat received FDA approval for treatment of soft-tissue sarcomas and lymphomas." (PMID 35852858, 2022). "Intriguingly, MYC and EZH2 create a positive loop that constantly leads to MYC and EZH2 overexpression, and both act together to silence tumor suppressor miRNAs in aggressive lymphoma cells, such as hsa-miR-150." (PMID 35008626, 2021). "This is consistent with findings suggesting that lymphoma cells, in particular, DLBCL, are sensitive to EZH2 depletion and EZH2 inhibitors." (PMID 34202528, 2021). "We tested the effects of two epigenetic modifiers, an EZH2 inhibitor, tazemetostat (EPZ6438) and a histone deacetylase inhibitor, panobinostat (LBH589) on SLFN11 expression in GCB-derived lymphoma cell lines." (PMID 33513156, 2021). "Remarkably, pharmacological inhibition of EZH2 promotes SESTRIN1 re-expression and restores its tumor suppressive activity, suggesting the possibility to epigenetically control mTORC1 activity in lymphoma." (PMID 34335584, 2021). "CPI-169, a previously disclosed indole based EZH2 inhibitor, shows significant antitumor activity and pharmacodynamic (PD) target engagement in a mouse xenograft model of a KARPAS-422 lymphoma while accompanied by limited oral bioavailability." (PMID 32723346, 2020). "The potent EZH2 inhibitor, EPZ005687, suppresses H3K27me3 in EZH2Y641/A677-mutant lymphoma in a dose-dependent manner." (PMID 32906688, 2020). "Therefore, EZH2-specific inhibitors may enhance the sensitivity of lymphoma cells to TRAIL." (PMID 35582230, 2020). "Prior research revealed that due to the synergic effect of BCL6 and EZH2 in lymphoma, targeting BCL6 and EZH2 together leads to a great therapeutic effect." (PMID 31903129, 2020). "Although EZH2, MYC, BCL2 and BCL6 are important prognostic biomarkers for lymphomas, our study shows that they poorly influence the sensitivity of lymphoma cell lines to DZNep-mediated apoptosis." (PMID 31419226, 2019). "EZH2 has also been shown to interact with transcription factors which are targets of tumor suppressor miRNAs, such as MYC in lymphomas and in MM." (PMID 28623912, 2017). "On the other hand, low level of EZH2 or reduced methylation at histone sites catalyzed by PRC2 may be oncogenic, for example, the recurrent Tyr 641 mutations in catalytic EZH2 SET domain, thought to impair activity, occur in two types of lymphomas arising from germinal center B cells." (PMID 27845897, 2017). "The anti-tumor efficacy of pharmacological EZH2 inhibition depends on SESTRIN1, indicating that mTORC1 control is a critical function of EZH2 in lymphoma." (PMID 29057015, 2017). "Addition of GSK126, a potent and selective small molecule inhibitor of EZH2 activity, decreases H3K27me3, reactivates PRC2-suppressed genes, such as, BLIMP1 (a tumor suppressor) and induces cytotoxicity in these lymphoma cells." (PMID 25605023, 2015). "We also note the increased sensitivity of the mutant EZH2 DB lymphoma cell line to HKMTI-1-005, in accordance with an EZH2 inhibitory effect." (PMID 26300989, 2015).
lymphoma (continued). "Knutson and colleagues were the first to describe potent phenotypic effects in lymphoma cell lines, following treatment with the SAM-competitive EZH2 inhibitor (EPZ005687)." (PMID 24622842, 2014). "Among the CHOP components, EPZ-6438 combinations with Prednisolone induced the strongest anti-proliferative activity, and this combination could also render refractory GCB lymphoma cell lines sensitive to EZH2 inhibition regardless of the EZH2 mutational status." (PMID 25493630, 2014). "Blocking EZH2 has shown promising outcomes, especially in lymphomas; however, targeting EZH2 has not yet demonstrated significant clinical activity in solid tumors." (PMID 40356745, 2025). "Although various EZH2 inhibitors have demonstrated promise in treating lymphoma, they have not fully managed to curb lymphoma cell proliferation despite effective reduction of the H3K27me3 mark." (PMID 37760442, 2023). "Furthermore, we subjected a panel of lymphoma cell lines to a small-molecule inhibitor of MEN1, MI-50354, and observed that compared to EZH2 wildtype, EZH2 mutant cells were significantly more sensitive to MEN1 inhibition." (PMID 37460547, 2023). "Tazemetostat selectively inhibits the H3K27me3 function of EZH2 but not the level of total EZH2 protein, and lymphomas have survival dependency on H3K27me3 function." (PMID 36446780, 2022). "Subsequently, catalytically hyperactivating mutations of EZH2 in somatic cells were identified in patients with non-Hodgkin lymphoma (NHL), indicating that PRC2 is critically involved in the progression of lymphoma." (PMID 36076977, 2022). "In addition, a recent study reported that EZH1 is globally distributed in the chromatin of aggressive lymphomas, and both EZH1 and EZH2 play critical roles in the chromatin regulation." (PMID 34771469, 2021). "Across a variety of lymphoma cell lines including Hodgkin's, non-Hodgkin's, and Burkitt lymphoma, DLBCL cells remained the most sensitive to EZH2 inhibition by GSK126, with seven out of 18 displaying sub-micromolar growth IC50s (28–861 nM) including both cytostatic and cytotoxic responses." (PMID 34458810, 2021). "Although EZH2 inhibitors are effective in treating sarcoma and lymphoma, other cancers that are dependent on EZH2, such as triple negative breast cancer (TNBC), do not respond to catalytic inhibition." (PMID 34617019, 2021). "Pathogenic variants were obvious in some of the most commonly affected genes in lymphomas, such as BCL2, MYD88, NOTCH2, EZH2, and CD79B, and most of them could be identified in matched LB-originated cfRNA." (PMID 34204385, 2021). "As EZH2 is responsible for H3K27 hyper-tri-methylation, the reduction in intracellular H3K27me3 levels following SHR2554 treatment was also examined in Pfeiffer lymphoma cell line." (PMID 34503063, 2021). "The EZH2 Y646 gain-of-function mutation was not identified in SDC, in contrast to reports of its presence in lymphoma." (PMID 35186711, 2021). "Concomitantly inhibitory action of both EZH2 and HDAC3 promoted transcriptional and epigenetic MYC-mediated repression of miR-29, resulting in down-regulation of miR-29 target pro-apoptotic genes and lymphoma growth suppression in vitro and in vivo." (PMID 32549409, 2020). "Targeting EZH2 has broad antitumor effects in pre-clinical cancer models, and specific drugs (Tazemetostat, GSK2816126 and CPI-1205) targeting EZH2 are currently in clinical trials for lymphomas and advanced solid cancers." (PMID 32923515, 2020). "Interestingly, the expression of PRC2 components EZH2, EED, and SUZ12 was lower in CD19+ normal B-cells as compared to that in lymphoma cell lines." (PMID 32850364, 2020). "As we showed recently, a mutant form of histone methyltransferase EZH2, responsible for transcriptional repression of multiple genes in cancer cells, inhibits expression of SESN1 in lymphomas and restoration of SESN1 expression in the tumors leads to suppression of lymphomagenesis in mice." (PMID 31857853, 2019).
lymphoma (continued). "In our study, we included KMT2D, CREBBP, EZH2, EP300, MEF2B, and TET2 in our lymphoma panel." (PMID 31403034, 2019). "This peptide is effective against EZH2-dependent MLL–AF9 leukemia and EZH2-mutant lymphoma cells, whereas it does not have any effect on non-transformed and EZH2 controls." (PMID 30510924, 2018). "Inhibition of EZH2 activity in the GC-derived DLBCL cells using a small molecule inhibitor was previously shown to reduce global H3K27me3 levels, induce the expression of BLIMP1 (a tumor suppressor) and impair the in vitro growth of lymphoma cells." (PMID 25605023, 2015). "For instance, we did not have access to lymphoma data, and failed to retrieve known Y641 mutants that increase the trimethylase activity of EZH2 in this cancer type." (PMID 25484917, 2014). "Since EPZ-6438 treatment alone does not strongly inhibit growth in EZH2 wild-type GCB lymphoma lines, we evaluated its ability to change the concentration-response curves of individual CHOP components." (PMID 25493630, 2014). "Combined inhibition of HDAC3 and EZH2 induced restoration of miR-29 and suppressed lymphoma cell growth, suggesting the MYC–EZH2–miRNA axis could be a promising target for epigenetic therapy in B cell lymphoma." (PMID 24348513, 2013). "Multiple factors, such as EZH2, c-MYC, IKZF1, IKZF3, IRF4, and CDK6, which are essential for the proliferation and survival of malignant plasma cells and lymphoma, were decreased upon treatment with PM in all tested MM and lymphoma cell lines, including MM1S, MM1R, and TMD-8." (PMID 40562746, 2025). "Ezh2 overactivation at the GC B-cell stage is not sufficient for lymphoma development, but earlier activation (CD19cre Ezh2Y641F/wt) could lead to aggressive lymphomas." (PMID 38022603, 2023). "EZH2 is involved in cancer initiation and progression mainly due to its transcriptional repression activity in the PRC2 complex, and gain-of-function (GOF) mutants of EZH2 (Y647F/N, A677G, and A687V) are frequently generated in several lymphomas, further promoting tumorigenesis." (PMID 36076977, 2022). "In addition, PRMT5, like EZH2, is required for GC formation and lymphoma survival through its interaction with BCL6, and thus, like EZH2, may also be important in the maintenance of epigenetic dysregulation in FL." (PMID 34193230, 2021). "Interestingly in mouse models attempting to recapitulate human disease, EZH2 overexpression in mice leads to myeloproliferative disorders rather than lymphomas." (PMID 33801781, 2021). "Defectively mutated RB fails to recruit EZH2 to diverse repeat DNA sequences as RB-EZH2 complex, disperses H3K27 tri-methylation from these genomic locations and permits repeat expression, thus conferring lymphoma susceptibilities." (PMID 31752930, 2019). "However, more specific EZH2 inhibitors including EPZ005687 and EPZ011989 are now available and have proved very successful at killing lymphoma cells, these new drugs may show therapeutic promise in EZH2 high HCC patients." (PMID 29079534, 2017). "Indeed, in a recent mouse model, it was shown that only the association of an EZH2 Y641 mutation and MYC overexpression, and not the EZH2 Y641 mutation alone, led to lymphoma development." (PMID 25762637, 2015). "Moreover, MYC was recently shown to interact with EZH2 and HDAC3 to repress miR-29 in lymphomas." (PMID 25644061, 2015). "Despite being recognized as an important target in lymphoma, the FDA-approved small molecule inhibitor tazemetostat targeting EZH2 has not yielded the expected outcomes." (PMID 37752998, 2023). "In contrast, no synergistic effect was observed in wild-type EZH2 DLBCL cell lines (OCI-LY-19, SU-DHL4, and Toledo) and other lymphoma types, such as mantle cell lymphoma (JeKo-1, Rec-1, Mino, and Z138) and Burkitt’s lymphoma (NC-37)." (PMID 32906688, 2020).
lymphoma (continued). "Although several studies have previously shown oncogenic role of mutant-EZH2 found in DLBCL and FL, studies aimed at understanding the role of wild type (wt) EZH2 in other lymphoma subtypes such as MCL, are lacking." (PMID 32850364, 2020). "A VHL-based PROTAC EZH2 degrader was subsequently tested in lymphomas; it was demonstrated to be more efficient than CRBN ligand-based degraders in degrading EZH2, showed advantages over common inhibitors in inhibiting tumor growth in lymphoma xenografts in vivo, and had no obvious toxicity." (PMID 36770884, 2023).
lung cancer (278 papers, 2011 to 2026). A malignant neoplasm involving the lung. "BACKGROUND: c-MYC and enhancer of zeste homolog 2 (EZH2) are key regulators of cell proliferation and epigenetic reprogramming and have been implicated in the pathogenesis and progression of lung carcinoma." (PMID 41928013, 2026). "PRC2 comprises four main subunits: EED, SUZ12, RBAP46/47, and EZH2, with EZH2 acting as the catalytic subunit which has been implicated in metastasis, particularly in breast, prostate, and lung cancers." (PMID 40016470, 2025). "The association between EZH2 overexpression and poor outcomes in lung cancer patients has been established." (PMID 40191732, 2025). "After comparing the NGS sequencing results of each group of samples, only 3 sites of EZH2 mutation were found in the primary lesion of lung cancer, while 20 mutation sites were found in metastatic cancer tissue." (PMID 38764053, 2024). "To delve deeper into the regulatory mechanisms underlying lung cancer progression, we identified EZH2 as a downstream target of NOP2 through RNA-sequencing and bioinformatics analysis." (PMID 39013911, 2024). "Analysis showed that GG genotype and GC genotype were risk factors for lung cancer brain metastasis.According to EZH2 mutation and immunohistochemical expression, the patients were divided into four groups." (PMID 38764053, 2024). "EZH2 G553C polymorphism contributes to the prediction of brain metastasis of lung cancer, in which G allele carriers are more prone to brain metastasis." (PMID 38764053, 2024). "Elevated EZH2 levels and an increased count of genes silenced via H3K27me3 were linked to the advanced stage of lung cancer." (PMID 38836056, 2024). "High-throughput sequencing found that EZH2 mutation was closely related to brain metastasis of lung cancer." (PMID 38764053, 2024). "We screened metastatic cancer, carcinoma in situ and their corresponding adjacent tissues by second-generation sequencing and detected the presence of high-frequency mutations in EZH2 in lung cancer primary lesions and brain metastatic tissues." (PMID 38764053, 2024). "Accumulating evidence indicated that the oncogenic effect of UTX loss is mediated mainly through an increase in the EZH2 level in lung cancer, and UTX loss sensitizes cells to EZH2 inhibition in multiple myeloma." (PMID 37679762, 2023). "It has been reported that upregulation of lncRNAs in lung cancer are associated transcript 1 (LUCAT1) which enhances cancer proliferation via EZH2 overexpression." (PMID 35236381, 2022). "EZH2 overexpression is associated with poor prognosis in lung cancer; therefore, it is considered an attractive therapeutic target." (PMID 33276757, 2020). "The effects of EZH2 on cell migration and invasion of lung cancer cells were determined via loss‐of functional assays." (PMID 31855281, 2020). "Since macrophage infiltration is reported to be associated with poor prognosis in lung cancer, we determined to detect the effect of EZH2 on macrophage infiltration of lung cancer." (PMID 31855281, 2020). "Here, we observed an inverse correlation of IRX1 and DNMT3A or EZH2 expression in primary lung cancers suggesting a causal relation between aberrant expression of epigenetic modifiers and IRX1 silencing." (PMID 33256112, 2020). "Studies have shown that exposure to tobacco smoke condensate induces increased the expression of EZH2 in cultured lung cancer cell lines, and DNA hypermethylation is a common risk factor for smoking behavior in NSCLC patients." (PMID 33299862, 2020). "This shows that, through the upregulation of the EZH2 expression, long noncoding RNA silences tumor suppressor genes and promotes lung cancer invasion and migration, which are associated with poor prognosis." (PMID 33299862, 2020). "Silencing and pharmacological inhibition of EZH2 in NCI-H1299 lung cancer cells caused reductions in LAT1 mRNA and protein." (PMID 30103560, 2018).